RNU6-521P (RNA, U6 small nuclear 521, pseudogene)
Gene: Small nuclear RNA gene on chromosome Y (7,423,054 to 7,423,158, reverse strand). Ensembl gene ENSG00000252472.
Homologues: Orthologues: chimpanzee U6 (100% identical), macaque U6 (92% identical), dog U6 (72% identical), pig U6 (72% identical). Paralogues in human: RNU6-114P (89% identical), RNU6-1152P (84% identical), RNU6-211P (83% identical), RNU6-310P (83% identical), RNU6-15P (82% identical), RNU6-19P (82% identical), RNU6-434P (82% identical), RNU6-1060P (81% identical), RNU6-1159P (81% identical), RNU6-116P (81% identical), RNU6-1287P (81% identical), RNU6-1316P (81% identical), and 1288 more.